PRL (prolactin)
Diseases named in the same sentence as PRL in open-access papers (continued):
Sharing a sentence is not in itself a finding about the gene and the disease.
breast cancer (continued). "Among women with schizophrenia/schizoaffective disorder, only exposure to ≥5 years of prolactin-increasing antipsychotics was associated with breast cancer (aOR = 1.48, 95% CI = 1.02–2.13)." (PMID 38687213, 2024). "A definitive association between the prolactin induced mammary tumors in rodents and the development or promotion of breast cancer in female patients with schizophrenia exposed to antipsychotics continues to be an area of debate." (PMID 38595824, 2024). "Extensive epidemiological research showed that a higher level of circulating PRL is linked with a greater risk of breast cancer and metastasis to premenopausal women." (PMID 39253602, 2024). "Using large-scale GWAS data, this study applied two-sample MR to explore the relationship between antidepressants overall and SSRI drugs, SSRI and prolactin levels, and the causal relationship between 5-HT and prolactin levels and breast cancer risk." (PMID 37540479, 2024). "Although causality remains uncertain, exposure to prolactin-elevating antipsychotics for ≥ 1 year was associated with increased odds of breast cancer in women with severe mental illness." (PMID 38687213, 2024). "The association between prolactin-increasing antipsychotics and breast cancer was further stratified by different cancer types, primary psychiatric diagnosis, and age group at the index date." (PMID 38687213, 2024). "High-normal circulating PRL levels increase breast cancer risk in both pre- and post-menopausal women(Tworoger, Eliassen, Rosner, Sluss, & Hankinson, 2004; Tworoger & Hankinson, 2006; M. Wang, Wu, Chai, Zhang, & Jiang, 2016)." (PMID 38660565, 2024). "Prior to these recently published studies, others have examined the association between prolactin increasing antipsychotics and breast cancer risk with mixed findings in both case-control and retrospective cohort designs." (PMID 38595824, 2024). "For other nonaffective psychotic disorders, exposure of 1–<5 years (aOR = 1.42, 95% CI = 1.16–1.74) and ≥5 years (aOR = 1.50, 95% CI = 1.24–1.81) to prolactin-increasing antipsychotics were both associated with increased breast cancer odds." (PMID 38687213, 2024). "Specifically, we estimated the relative risk of a new diagnosis of breast cancer among new users of high prolactin increasing antipsychotic drugs (HPDs) compared with new users of non/low prolactin increasing drugs (NPDs)." (PMID 38595824, 2024). "There was a positive causal relationship between prolactin levels and breast cancer (IVW, P = 0.02, OR = 1.058) and ER-positive breast cancer (Weighted median, P = 0.043, OR = 1.141; IVW, P = 0.009, OR = 1.125)." (PMID 37540479, 2024). "In mammary cancer cells, prolactin causes elevation of intracellular ferrous iron pools (also known as labile iron pools) through the upregulation of the surface receptor CD44." (PMID 39201626, 2024). "The increased levels of prolactin are supposed to be harmful to females and thought to increase the risk of development of breast cancer in the life of females." (PMID 37900385, 2023). "Population-based studies in post-menopausal women have also shown a positive correlation between plasma PRL levels and breast cancer risk." (PMID 36833950, 2023). "Taipale and collaborators, as a part of the Finnish nationwide register of patients in hospital treatment, carried out a case–control study investigating the effect of prolactin-raising antipsychotics on the risk of breast cancer in schizophrenia populations." (PMID 37759839, 2023). "High exposure of breast tumors to prolactin has been associated with an increased risk of breast cancer, particularly estrogen receptor-positive cancers." (PMID 37296899, 2023). "Breast cancer overexpresses the hormone prolactin, and prolactin is implicated in breast cancer growth, metastasis, and chemoresistance." (PMID 36650218, 2023).
breast cancer (continued). "Some of the variables include the many risk factors for breast cancer to which these women are exposed and the uncertainty about which antipsychotics elevate prolactin, and to what degree." (PMID 37759839, 2023). "We did not observe clear differences in the association between plasma prolactin and breast cancer risk by tumor expression of PRLR or pJAK2, although associations for premenopausal women were observed for pSTAT5 positive tumors only." (PMID 36882838, 2023). "The hormone prolactin is supposed to increase the risk of breast cancer development in a female's life." (PMID 37900385, 2023). "Women who used prolactin-raising antipsychotics for more than 5 years have a 150% increased risk for breast cancer, which is especially worrisome since female SSD patients are already at increased genetic risk for this disease." (PMID 37864676, 2023). "Given the different associations of prolactin with breast cancer risk by menopausal status, we examined these associations separately in premenopausal and postmenopausal women." (PMID 36882838, 2023). "Evidence from both laboratory and epidemiologic studies supports that prolactin is involved in mammary tumorigenesis, with stronger associations for postmenopausal breast cancer that led to improvements in risk prediction models." (PMID 36882838, 2023). "Overall, we did not observe clear differences in the association of circulating prolactin levels and risk of breast cancer by expression of PRLR or downstream markers of prolactin receptor activation, pJAK2 and pSTAT5." (PMID 36882838, 2023). "The administration of CysA has been shown to decrease plasma prolactin levels rapidly, and the mammary glands' prolactin function has a correlation with the incidence of mammary tumor caused by radiation." (PMID 37731680, 2023). "Recently, an analysis of the association between cumulative exposure to prolactin-increasing drugs and breast cancer was published." (PMID 36833950, 2023). "High levels of endogenous hormones such as estrogens, androgens, and prolactin increase breast cancer risk." (PMID 36980159, 2023). "Despite an overall lack of association between circulating prolactin levels and risk of breast cancer in premenopausal women, we observed that prolactin was positively related to a higher risk of pSTAT5 positive breast cancer in this population." (PMID 36882838, 2023). "Some researchers believe that some antipsychotics increase the risk of breast cancer by increasing serum PRL levels, as PRL stimulates the proliferation of breast tumors." (PMID 36591471, 2022). "Due to the autocrine/paracrine of PRL, although the pooled data suggest that PRL-increasing and PRL-sparing antipsychotics pose a similar risk of breast cancer, we cannot deny the role of PRL in breast cancer." (PMID 36591471, 2022). "PRL cooperates with estrogen, a well-recognized risk factor for breast cancer, by multiple mechanisms, including reciprocal upregulation of the other’s receptors, and downstream crosstalk." (PMID 35784527, 2022). "Antipsychotic use is moderately associated with breast cancer, possibly mediated by prolactin-elevating properties of certain medications." (PMID 36059215, 2022). "Currently, we have no exact cause for breast cancer, but increasing evidence shows that endogenous estrogens, progestogens and other hormones (e.g., androgens and prolactin) are linked to the development of breast cancer." (PMID 36005209, 2022). "Additional analyses of this cohort found that the association of circulating PRL in the highest quartile in postmenopausal women ten years prior to diagnosis was strongest for aggressive ER+ breast cancer." (PMID 35784527, 2022). "Evidence shows a further extent of exposure to antipsychotics, such as a longer duration of use, is associated with a higher risk of breast cancer, particularly for antipsychotics with prolactin-elevating properties." (PMID 36059215, 2022).
breast cancer (continued). "Strong epidemiologic data linking higher levels of circulating PRL to increased risk for ER+ breast cancer are supported by multiple lines of experimental evidence." (PMID 35784527, 2022). "In conclusion, we found a moderate association between the use of antipsychotics and breast cancer with a more evident association observed with prolactin-elevating medications and greater extent of antipsychotic exposure." (PMID 36059215, 2022). "Our review helps to determine the association between antipsychotics and breast cancer and the role of PRL." (PMID 36591471, 2022). "In fact, other conditions that lead to high circulating levels of PRL (~200 ng/mL) such as breastfeeding have been linked to reduced risk of breast cancer." (PMID 36157462, 2022). "Large prospective epidemiologic studies have linked higher prolactin exposure to increased risk, particularly for ER+ breast cancer in postmenopausal women." (PMID 35784527, 2022). "Large prospective studies have linked higher levels of circulating PRL within the normal range to increased risk for breast cancers which express estrogen receptor alpha (ER+) in postmenopausal, or premenopausal women." (PMID 35784527, 2022). "They reported that users of antipsychotics with medium and high prolactin-elevating properties were significantly associated with breast cancer development." (PMID 36059215, 2022). "One potential reason is that studies on the relationship between PRL levels and breast cancer risk have only focused on circulating PRL levels." (PMID 36591471, 2022). "Conversely, prior prospective studies have linked prolactin with increased postmenopausal women breast cancer risk, but our results in this comprehensive study shows that these associations are weak or null as a whole." (PMID 36425551, 2022). "Epidemiological studies examining the normal physiological levels of circulating PRL (2-29 ng/mL) have implicated PRL as a risk factor and is involved in breast cancer etiology." (PMID 36157462, 2022). "Recently, several epidemiological studies showed that prolactin-elevating antipsychotics increase the risk of breast cancer and breast cancer-specific mortality." (PMID 35804859, 2022). "After 20 years of follow‐up, the finding has demonstrated an association of prolactin levels <10 years before diagnosis and breast cancer risk of postmenopausal women, especially for ER(+) tumours and metastatic disease." (PMID 34651424, 2021). "There have been several reports on the relationship between breast cancer and antipsychotics, and higher blood prolactin levels are associated with a higher risk of breast cancer, especially hormone receptor-positive and postmenopausal breast cancers." (PMID 33789764, 2021). "In breast cancer cells, the association between prolactin exposure and development of invasive breast cancer is widely accepted." (PMID 34294140, 2021). "STAT5a and PRL are both implicated in dysregulating apoptotic machinery in breast cancer cells, which was confirmed in our pathway analysis of the MCF7 STAT5a mutants RNA-seq data 24,45–47." (PMID 34188118, 2021). "While a handful of recent studies have suggested a role for this receptor in TNBC, PRL/hPRLr have traditionally been associated with luminal breast cancers, and this association is observed with only hPRLrL6,26,29." (PMID 33772010, 2021). "In conclusion, an effective mechanism for reducing the levels of GH and PRL would therefore provide a powerful tool for decreasing breast cancer risk." (PMID 34206988, 2021). "High circulating levels of its ligand, PRL, correlate with increased risk for developing breast cancer and with disease progression and reduced response to tamoxifen." (PMID 34107902, 2021). "There have been a number of studies on the association of PRL and its receptors with benign and malignant breast tumors." (PMID 34945164, 2021).
breast cancer (continued). "Both compounds abrogated PRL-induced proliferation and invasion of breast cancer cells (BCC), as well as lymphocyte proliferation and caused no apparent in vitro and in vivo cytotoxicity." (PMID 34071395, 2021). "In this large population-based study, we observed increases in breast cancer-specific mortality among patients using antipsychotics after diagnosis, with marked associations observed for prolactin-elevating antipsychotics." (PMID 32831062, 2020). "In contrast, researchers have argued that the published data linking prolactin to breast cancer risk and progression are unconvincing and insufficient to deprive breast cancer patients of antipsychotic treatment." (PMID 32831062, 2020). "In women, elevated levels of prolactin correlate with increased breast cancer risk and metastasis, whereas lower levels of prolactin/PRLR in clinical samples associate with improved patient survival." (PMID 33335078, 2020). "In breast cancer patients, high prolactin levels pre-treatment have also been associated with increased treatment failure, recurrence and decreased survival." (PMID 32831062, 2020). "This study revealed that the loss of concomitant expression of the PRL and TGFβ receptors occurs during breast cancer progression." (PMID 30987013, 2019). "Mammary cell differentiation caused by PRL-PRLR-JAK2-STAT5 signaling is a mechanism by which an early-age pregnancy reduces breast cancer risk." (PMID 29778097, 2018). "Selective serotonin reuptake inhibitors (SSRIs), the first-line pharmacological treatment for depression, have been implicated in breast cancer development through increased prolactin levels and tamoxifen metabolism inhibition." (PMID 29351761, 2018). "The ‘High-Hormone’ profile was positively loaded by serum prolactin and progesterone, which are positively associated with postmenopausal breast cancer in case-control, prospective, and cross-sectional studies." (PMID 30572623, 2018). "We cannot rule out a causal relationship as preclinical studies have demonstrated that SSRIs increase prolactin levels, an accepted risk factor for breast cancer progression, and facilitate metastasis." (PMID 29351761, 2018). "It is unlikely that changes in prolactin levels mediate the reduced risk of breast cancer development in post-menopausal women associated with increased physical activity at any level." (PMID 28717404, 2017). "Our analyses were motivated by the strong animal and in vitro data supporting an important role of prolactin in breast carcinogenesis and epidemiologic data suggesting an association of increased levels with breast cancer risk." (PMID 28717404, 2017). "In a separate study of MCF-7 and T47D breast cancer cells on collagen I-coated PA gels of varying stiffness, the authors linked increased proliferation on stiff substrates to prolactin signaling." (PMID 29136040, 2017). "We observed a stronger association between OPG and ER– breast cancer risk among women with relatively high circulating prolactin concentrations." (PMID 28173834, 2017). "Prolactin plays an important role in mammary gland development and lactation and has been implicated in the etiology of breast cancer." (PMID 28212313, 2017). "It is unlikely that changes in prolactin levels mediate the reduced risk of breast cancer development in post-menopausal women associated with increased levels of physical activity." (PMID 28717404, 2017). "The development and progression of estrogen receptor alpha positive (ERα+) breast cancer has been linked epidemiologically to prolactin." (PMID 28103936, 2017). "Collectively, these results strongly suggest that plasma prolactin functions as an important pathogenic factor that contributes to the etiology of breast cancer." (PMID 27184120, 2016). "PubMed and Medline were used to search and identify published observational studies that assessed the relationship between plasma prolactin levels and the risk of breast cancer." (PMID 27184120, 2016).
breast cancer (continued). "Foremost, our study represents the first attempt to assess the relationship between plasma prolactin levels and the risk of breast cancer by combining all observational studies." (PMID 27184120, 2016). "When combined using a fixed-effects model, we revealed a statistically significant positive relationship between plasma prolactin levels and risk of breast cancer, with the RR (95% CI) being 1.16 (1.04, 1.29) (P < 0.05)." (PMID 27184120, 2016). "Our results demonstrated a positive relationship between plasma prolactin levels and the risk of breast cancer." (PMID 27184120, 2016). "In conclusion, the present study provides evidence supporting a significantly positive association between plasma prolactin levels and the risk of breast cancer." (PMID 27184120, 2016). "Large prospective human studies identified an association of high PRL serum levels with breast cancer risk." (PMID 27782069, 2016). "It has to be noted that although we identified a significant positive association between plasma prolactin levels and the risk of breast cancer, the mechanisms underlying this relationship remain entirely elusive." (PMID 27184120, 2016). "In subgroup analyses, we found a positive association between plasma prolactin levels and the risk of breast cancer among the patients who were postmenopausal, ER+/PR+ or in situ and invasive carcinoma." (PMID 27184120, 2016). "Our results suggested that plasma prolactin levels were associated with an increased risk of breast cancer, particularly for those who are diagnosed as the ER+ subtype and postmenopausal patients." (PMID 27184120, 2016). "The PRLR has been found in the vast majority of human breast cancers and PRL signaling has been implicated in breast cancer cell proliferation, survival, motility and angiogenesis." (PMID 27542844, 2016). "Previous studies suggest that higher levels of plasma prolactin are associated with escalated risk of breast cancer, however, these results are contradictory and inconclusive." (PMID 27184120, 2016). "Both PAK1 and the hormone/cytokine prolactin (PRL) have been implicated in breast cancer cell motility, however, the exact mechanisms guiding PRL/PAK1 signaling in breast cancer cells have not been fully elucidated." (PMID 27542844, 2016). "In the present study, 7 eligible studies were identified and combined to interrogate the association between plasma prolactin levels and the risk of breast cancer." (PMID 27184120, 2016). "With this strategy, we revealed a positive association between plasma prolactin levels and the risk of breast cancer." (PMID 27184120, 2016). "In breast cancer patients, high PRL is associated with an overall worse survival and with an increase in the occurrence of breast cancer metastasis." (PMID 27782069, 2016). "Meanwhile, our systemic interrogation uncovered a positive association between plasma prolactin levels and the risk of breast cancer in both primary and invasive tumors." (PMID 27184120, 2016). "We also performed subgroup analyses to assess how various factors influence the relationship between plasma prolactin levels and risk of breast cancer." (PMID 27184120, 2016). "Lastly, our results also revealed a positive correlation between plasma prolactin levels and risk of breast cancer among the cohort studies (RR (95% CI) as 1.17 (1.05, 1.31))." (PMID 27184120, 2016). "Despite the inclusion of these studies, however, the positive association between plasma prolactin levels and the risk of breast cancer remains to be identified, which suggests that our results are robust." (PMID 27184120, 2016). "Steroid levels were not influenced by their corresponding receptor expression in mammary neoplasms, but increased PRL levels were negatively associated with low PRLR gene expression in malignant tumors." (PMID 26370564, 2015).